CTSL (cathepsin L)
Diseases named in the same sentence as CTSL in open-access papers (continued):
Sharing a sentence is not in itself a finding about the gene and the disease.
tumor (continued). "However, tumor cell intrinsic events, including Myc-mediated regulation of cathepsin L expression, might be different between these two models, as the RT2 and the MycERTAM;Bcl-xL PNET cancer cells are driven by distinct oncogenes, the SV40 antigen and activated c-Myc, respectively." (PMID 25927437, 2015). "While some family members such as cathepsins B, C and S, are supplied to the PNET tumor site by CD45+ inflammatory cells, cathepsin L is predominantly expressed by insulin-producing cancer cells." (PMID 25927437, 2015). "In addition, as determined by immunohistochemistry, the incidence of CTSL protein expression in poor-differentiated carcinoma was significantly higher than that in well-differentiated tumors, suggesting that high level of CTSL expression was related to poor tumor differentiation." (PMID 25384089, 2014). "In vitro experiments demonstrated that over-expression of CTSL in MHCC-97H cells promoted cell proliferation and tumor progression ability." (PMID 25384089, 2014). "The results showed that CTSL expression, serum AFP, tumor size, tumor recurrence and stage were recognized as independent prognostic factors of survival." (PMID 25384089, 2014). "Furthermore, western blot also confirmed the aberrant expression of CTSL, CTSD, HSPA8, and XRCC4 in tumor tissues relative to paracancerous normal tissues." (PMID 41399382, 2026). "CTSL as an EMT regulator alters the aggressiveness and migration of tumor cells." (PMID 37480054, 2023). "Cluster 2 may consist of pro-tumor macrophages with the specific expression of MARCO and PLAUR (expressing e.g., CTSL, MARCO and PLAUR) and the proportion was significantly increased compared with N group." (PMID 37153595, 2023). "We found that mRNA expression of HSPA5 was the highest, followed by FURIN and CTSL in the majority of the tumor tissues, and ACE2 expression was the lowest, demonstrating that CTSL might facilitate tumorigenesis and SARS-Cov-2 entry in most cancers." (PMID 35414771, 2022). "Similarly, it was demonstrated in vivo that the injection of CTSL-overexpressing HCC (MHCC-97-H) cells into mice resulted in increased growth and tumor weight compared to the control." (PMID 36289617, 2022). "Based on the distribution of CTSL isoform expression and usage, we concluded that CTSL-002 might play a major role in tumor progression and SARS-CoV-2 entry in different kinds of tumor tissues." (PMID 35414771, 2022). "Similarly, cotreatment with CTSL inhibition and ADM in M-NSG mice of subcutaneous tumors exhibited less tumor growth." (PMID 36133820, 2022). "Notably, the first heat resulted in a 1.7-fold higher amount of DXR in the tumor of mice who received CTSL compared to TSL, whereas in the one-step extravascular release, both liposomes created identical DXR levels in the B16BL6 tumor." (PMID 36297598, 2022). "As such, a role for WT EpCAM in the regulation of CTSL in normal epithelia and/or cancer (as demonstrated here) is consistent with the known roles for EpCAM in the regulation of both epithelial-to-mesenchymal transition (EMT) and tumor cell invasion." (PMID 33980181, 2021). "Interestingly, most tumor types exhibited weaker ACE2/TMPRSS2 and ACE2/CTSB correlations compared to normal tissue, whereas the ACE2/CTSL and ACE2/FURIN correlations in normal tissue are weaker than that of most cancer types." (PMID 33707526, 2021). "In agreement with the mixed normal and tumor datasets, PBMC displayed positive correlations between ACE2/TMPRSS2, TMPRSS2/FURIN, ACE2/TFRC, FURIN/TFRC, TMPRSS2/CTSL, FURIN/CTSL, TMPRSS2/MYC, and FURIN/AKT1 and a negative association between ACE2/ADAM17." (PMID 33796097, 2021). "CTSB, CTSL, and FURIN expression was increased in most tumor types relative to normal tissue." (PMID 33707526, 2021). "However, the mRNA levels of CTSL, HNRNPK, LRIG1, and OSBPL5 were significantly downregulated in the tumor tissues compared to those observed in normal tissues." (PMID 35284334, 2021).
tumor (continued). "In vitro and in vivo, we could show that the p110 CUX1 variant, resulting from proteolytic cleavage of full-length p200 CUX1 by cathepsin L, was active in PDAC and enhanced tumor development in concert with oncogenic Ras." (PMID 34070180, 2021). "We then analyzed CTSL and CTSS in plasma to compare systemic and tumor levels." (PMID 33042834, 2020). "In our study, we found that CTSL could proteolytically cleave the CDP/Cux p200 and generate CDP/Cux p110, which contributed to the transcriptional activation of VEGF-D and promoted tumor angiogenesis in GC." (PMID 32388635, 2020). "Notably, the nuclear CTSL activates the transcription of EMT genes and also confers a replicative and metastatic advantage to tumor cells." (PMID 30732622, 2019). "Additionally, CTSL knock-down in A549 cells favored mesenchymal to epithelial transition (MET) in vivo, inhibiting xenograft tumor growth." (PMID 31340550, 2019). "Cathepsin L plays an important role in degrading the ECM and promoting tumor invasion." (PMID 27127880, 2016). "Besides CTSB, other CTSs, such as cathepsin D (CTSD), cathepsin L (CTSL) and cathepsin S (CTSS), showed highly expression in invasive tumor and increase motility of cancer cells." (PMID 27031837, 2016). "We conclude that cathepsin L is required for tumor maintenance and progression, rather than tumor initiation, during neuroendocrine tumorigenesis involving Myc-driven proliferation." (PMID 25927437, 2015). "Besides CTSL expression level, age, tumor size, serum AFP, stage, tumor recurrence and tumor differentiation were also significantly correlated with overall survival in univariate analysis." (PMID 25384089, 2014). "Without adjusting for epithelium percentage, both EpCAM and CTSL levels appeared significantly higher in tumor tissues than normal tissues with a p value less than 0.001." (PMID 24289299, 2013). "The patient variability for cathepsin L is shown as well but was not as consistently low for the normal specimens or as consistently high for the tumor specimens." (PMID 21756348, 2011). "Irrespective of HER2 expression status, both tumor and stromal compartments of invasive breast cancers exhibit high levels of CTSL, which efficiently cleaves T-DXd’s specialized linker, enabling payload release and exerting cytotoxic effects against HER2-low or HER2-negative tumors." (PMID 41425250, 2025). "This indicates that p110 promotes tumor progression, whereas p200, in the absence of cathepsin L, might exert tumor-suppressive actions." (PMID 34070180, 2021). "Whether or not the complement system is involved in the latter anti-tumor effects of the anti-cathepsin L treatment remains unresolved." (PMID 31024572, 2019). "However, it is not known which cell population produces the cathepsin L that is important for macrophage-stimulated tumor cell invasion." (PMID 31565189, 2019). "However, in both cancer models tumor progression is significantly altered in cathepsin L knock-out mice receiving wild-type bone marrow, suggesting a role for tumor cell-derived cathepsin L or cathepsin L expressed by non-myeloid cells of the tumor stroma." (PMID 22798952, 2012). "We speculated that resistant cells have nuclear localization of CTSL due to the lack of steffin B (CSTB), as evidenced in an advanced tumor microarray." (PMID 36291907, 2022).
cancer (127 papers, 2007 to 2025). A tumor composed of atypical neoplastic, often pleomorphic cells that invade other tissues. "When mutated, approximately half of all cancer-associated EpCAM mutations localize to the cytosolic compartments, where it cannot inhibit extracellular cathepsin-L." (PMID 37192201, 2023). "It has been reported that cathepsin L (CTSL) is expressed by several cancerous tissues that regulates cancer progression and increases the susceptibility to SARS-CoV-2 infection." (PMID 37142998, 2023). "High levels of CTSL transcription have been identified as a significant risk factor for mortality in various cancer types, including HNSC, indicating a poor prognosis." (PMID 37292206, 2023). "During our previous study, we generated several cancer-associated EpCAM mutations to test the effect of cytosolic EpCAM expression on cathepsin-L protease activity." (PMID 37192201, 2023). "CTSL is expressed by cancerous tissues and encodes a lysosomal cysteine proteinase that regulates cancer progression and SARS-CoV-2 entry." (PMID 35414771, 2022). "In the current study, we analyzed CTSL expression, mutation rate, survival and COVID-19 disease outcomes in cancer and normal tissues, using online databases." (PMID 35414771, 2022). "Due to frequent gene mutations in tumors, the mutative status of CTSB and CTSL were analyzed in pan-cancers." (PMID 35155389, 2022). "Together, these results demonstrate that secreted EpCAM inhibits secreted CTSL activity, while cancer-associated EpCAM mutations that prevent cell surface expression also prevent the ability to inhibit CTSL activity." (PMID 33980181, 2021). "CTSL is involved in autophagy and phage maturation-related pathways and associated with many cancers." (PMID 34476221, 2021). "In this context, previous studies have shown that increased expression and nuclear translocation of cathepsin L is associated with induction of epithelial–mesenchymal transition, which in turn can increase cancer metastasis and cause drug resistance." (PMID 34065077, 2021). "To investigate the possible SARS-CoV-2 infection risk of pan-cancer, we analyzed the genetic alterations, RNA expression, DNA methylation, and the association with immune subtypes of ACE2 and CTSL/B with the prognosis in pan-cancer." (PMID 33231569, 2020). "Overexpression and secretion of the enzymes cathepsin D (CathD) and cathepsin L (CathL) is associated with metastasis in several human cancers." (PMID 30845739, 2019). "CTSL upregulation has been found in many cancers to be positively associated with cancer invasion and metastasis and poor prognosis." (PMID 31632196, 2019). "For example, increased serum levels of cathepsin L are associated with metastatic stage of different cancer types and poor patient prognosis." (PMID 28611951, 2017). "Cathepsin B is associated in the invasion process in many types of cancer and these data confirmed the essential role of this cathepsin, in contrast to cathepsin L and cathepsin K in GBM invasion." (PMID 28424417, 2017). "Upregulation of the expression of cathepsin L is detected, and it is considered to be a hallmark, in both cancer and progeria." (PMID 24073275, 2013). "Besides being involved in cancer development, CTSL was also implicated in other diseases such as chronic kidney disease, cardiovascular diseases, and type 2 diabetes." (PMID 38944813, 2024). "Cathepsin L (CTSL) encodes a lysosomal cysteine proteinase that regulates cancer progression." (PMID 39619695, 2024). "Therefore, it is essential to evaluate the correlation between disease outcomes and CTSL expression in cancer tissues and predict the susceptibility of cancer patients to SARS-CoV-2." (PMID 37292206, 2023). "Taken together, our findings and these recent preclinical studies suggest that CTSL inhibition in cancers harboring EpCAM mutations may prove to be an effective strategy." (PMID 33980181, 2021).
cancer (continued). "Cancers harboring cancer-associated EpCAM mutations and/or EpCAM silencing may have increased CTSL activity." (PMID 33980181, 2021). "This study aimed to help fill in the gaps in our understanding of the molecular mechanisms that underly the role of secreted cathepsin B and cathepsin L in cancer metastasis and to determine if there is a link between plasma membrane V-ATPases and the activity of these secreted cathepsins." (PMID 28766149, 2017). "Cathepsin L secretion is associated with late stage and malignant tumors." (PMID 28766149, 2017). "Elevated levels of CTSL are reported to be associated with a variety of malignant tumor." (PMID 27351223, 2016). "Cathepsin L (CTSL) is overexpressed in various cancers, however, the association between CTSL expression and paclitaxel resistance remains unclear." (PMID 27351223, 2016). "CTSL, a lysosomal endopeptidase expressed in most eukaryotic cells, is a member of the papain-like family of cysteine proteinases, which is reported to be associated with cancer tumorigenesis, proliferation and migration." (PMID 27351223, 2016). "Additionally, other studies have reported that excessive accumulation of CTSL in intracellular and extracellular spaces regulates downstream targets and protein cascades associated with various malignant cells, impacting cancer cell apoptosis, angiogenesis and metastasis." (PMID 41261048, 2025). "Evidence shows that CTSL expression may be linked to cancer grade and stage." (PMID 34885040, 2021). "To investigate whether cancer-associated EpCAM mutations affect its cellular localization, and/or its potential to inhibit CTSL, we cloned multiple cancer-associated EpCAM mutations in expression vectors alone, or fused to GFP at the C-terminal, and tracked EpCAM localization in vitro." (PMID 33980181, 2021). "CTSL expression may be linked to cancer grade, invasion and stage." (PMID 34476221, 2021). "Collectively, these findings demonstrate that USP20 promotes EMT, migration, drug resistance and cancer stemness through upregulating CTSL expression, highlighting its potential as a therapeutic target in HNSCC." (PMID 41261048, 2025). "CTSL is highly expressed in many malignant tumours, including gastrointestinal stromal tumours and metastatic bone tumours, and is considered a potential diagnostic or prognostic marker." (PMID 39893643, 2025). "Pan‐cancer analysis across TCGA datasets revealed that USP20 and CTSL expression were particularly associated with unfavourable prognosis in HNSCC, among other cancer types." (PMID 41261048, 2025). "USP20 mediates the deubiquitination and stabilization of CTSL, thereby promoting epithelial‐to‐mesenchymal transition and cancer stem cell renewal, ultimately enhancing metastatic potential and chemoresistance." (PMID 41261048, 2025). "Cathepsin L1, also identified here, cleaves perlecan, a proteoglycan protein which inhibits the growth and invasiveness of cancer cells and of angiogenesis." (PMID 41300368, 2025). "Remarkably, in gastric cancer, it has been demonstrated that the proteolytic processing of CDP/Cux by nuclear CtsL induces angiogenesis by altering the gene expression pattern, thus promoting cancer cell survival." (PMID 39851495, 2025). "CtsL is one of the best studied lysosomal proteases regarding its nuclear activity not only in cancer, but also under physiological conditions." (PMID 39851495, 2025). "Cancer patients with up-regulated CTSL have a worse prognosis and are more likely to have aggressive metastases." (PMID 39619695, 2024). "Transmembrane protease serine 2 (TMPRSS2), angiotensin-converting enzyme 2 (ACE-2), and other host cell proteases including cathepsin L, which is frequently expressed in cancer patients, are known to enhance COVID-19 infection." (PMID 36675457, 2023). "This study employed in silico strategies, including a combination of machine learning (ML) and structure-based screening of natural compounds, to find natural CTSL inhibitors for combating cancer." (PMID 38139037, 2023).
cancer (continued). "ZINC4097985 and ZINC4098355 exhibit potential as viable inhibitors of CTSL, thereby offering therapeutic value in the management of cancer." (PMID 38139037, 2023). "CTSL’s ability to degrade E-cadherin (a cell–cell adhesion molecule) contributes to cancer cells’ invasive function and metastatic capacity." (PMID 38139037, 2023). "ZINC4097985 and ZINC4098355 can be considered promising candidates for CTSL inhibition after experimental validation, with the potential to provide therapeutic benefits in cancer management." (PMID 38139037, 2023). "CTSL expression increases in various cancers, including glioma, melanoma, pancreatic, breast, and prostate carcinoma." (PMID 38139037, 2023). "Studies on animal models of pancreatic cancer have demonstrated that CTSL and cathepsin S enzymes are released from cancer cells and act on the extracellular domain of cell adhesion molecules present on the surface of cancer cells." (PMID 38139037, 2023). "This study used a novel approach that combined ML and SBVS techniques to identify potential natural CTSL inhibitors, the expression of which is known to be abnormal in a variety of cancer types." (PMID 38139037, 2023). "Similar results were reported in cancer research, where cathepsin-L is well known to be involved in rapid cell proliferation." (PMID 37047535, 2023). "The acidic environment created in cancer cells by anaerobic glycolysis promotes the activity of CTSL, which actively degrades collagen, fibronectin, and laminin." (PMID 38139037, 2023). "We also discovered that HMGB1-mediated CTSL and autophagy-lysosome pathway blockade in cancer cells plays vital roles in the antitumor effects by inhibiting the formation of the Beclin-1-PI3K-III complex." (PMID 37537587, 2023). "To explore the possibility of using CD or m62A as therapeutics against SARS-CoV-2, we analyzed the change in the expression of CTSL protein in cancer cell lines treated with these agents." (PMID 35414771, 2022). "Thus CTSL mutations may further regulate SARS-CoV-2 entry in cancer tissue." (PMID 35414771, 2022). "Our results show that the immune cell infiltration was correlated with CTSB expression in most cancer types and CTSL expression in a part of the cancer types (COAD, STAD, LUAD, and LUSC) (respectively)." (PMID 35155389, 2022). "Going forward, we quantitatively compared CTSL mRNA expression profiles from thirty-three types of cancers and their matched normal tissues, including those of breast and lung." (PMID 35414771, 2022). "We show that the mRNA expression of CTSL is 66.4-fold higher in normal lungs and 54.8-fold higher in cancer tissues, as compared to ACE2 mRNA expression in the respective tissues." (PMID 35414771, 2022). "Among them, SnuCalCpI03 displayed remarkable inhibition of lung, colon, breast, pancreatic, and prostatic cancer cell invasion by interacting with cathepsin L secreted from cancer cells." (PMID 35388095, 2022). "CTSL up-regulation has been identified in many human malignancies including gastric and lung cancers." (PMID 36133820, 2022). "We found that CTSL is conserved across different species, and highly expressed in both normal and cancer tissues from human, as compared to ACE2 or other proteinases/proteases." (PMID 35414771, 2022). "Since cathepsin L is upregulated in different tumors and can facilitate cancer cell migration, many studies have been conducted to study it as a possible anti-metastasizing drug target." (PMID 41541591, 2022). "Upregulation of CTSL correlates with metastatic aggressiveness and poor prognosis in cancer patients." (PMID 35414771, 2022). "Regulation of CTSL expression by Chinese medicine has shown its potential role in tumorigenesis, cancer progression and SARS-CoV-2 infection." (PMID 35414771, 2022). "Considering the role of CTSD and CTSL in other cancer types and their overexpression in HCC, these data suggest that these cathepsins also stimulate invasion and metastasis in the context of HCC." (PMID 36289617, 2022).